TRIM31 (tripartite motif containing 31)
Description:
E3 ubiquitin-protein ligase that acts as a regulator of antiviral immune response and inflammation by mediating ubiquitination of substrates. Acts as a regulator of innate immune defense against viruses by mediating 'Lys-63'-linked ubiquitination of MAVS, promoting MAVS polymerization and formation of three-stranded helical filaments on mitochondria. Acts as a negative regulator of the NLRP3 inflammasome by catalyzing 'Lys-48'-linked ubiquitination of NLRP3, leading to its degradation. Regulator of Src-induced anchorage independent cell growth (By similarity).
Synonyms: C6orf13; RNF; HCGI; HCG1
Tractability: PROTAC: UniProt records ubiquitination sites on it.
Gene: Protein-coding gene on chromosome 6 (30,102,886 to 30,113,090, reverse strand). Ensembl gene ENSG00000204616.
Subcellular location: Cytoplasm; Mitochondrion
Pathways (Reactome):
Immune System: Interferon gamma signaling
Gene Ontology:
Molecular function: protein binding; transcription coactivator activity; ubiquitin protein ligase activity; zinc ion binding
Biological process: antiviral innate immune response; defense response to virus; host-mediated suppression of symbiont invasion; negative regulation of NLRP3 inflammasome complex assembly; protein K48-linked ubiquitination; protein K63-linked ubiquitination; ubiquitin-dependent protein catabolic process; innate immune response; positive regulation of DNA-templated transcription; protein ubiquitination
Cellular component: cytoplasm; mitochondrion; cytosol
Genetic constraint (gnomAD): Loss-of-function variants: 29 observed, 41.63 expected, observed/expected ratio (o/e) 0.7, 90% interval 0.52 to 0.95. The upper end of that interval is the gene's LOEUF score, 0.95, which puts it in group 4 of 6, group 1 being the genes least tolerant of losing a copy. Missense variants: 453 observed, 518.87 expected, observed/expected ratio (o/e) 0.87, 90% interval 0.81 to 0.94. Synonymous variants: 162 observed, 204.79 expected, observed/expected ratio (o/e) 0.79, 90% interval 0.69 to 0.9.
Homologues: Orthologues: chimpanzee TRIM31 (99% identical), mouse Trim31 (44% identical), rat Trim31 (43% identical). Paralogues in human: TRIM39 (22% identical), TRIM26 (22% identical), TRIM75 (21% identical), TRIM41 (21% identical), TRIM58 (21% identical), TRIM10 (20% identical), TRIM11 (20% identical), TRIM21 (20% identical), TRIM4 (20% identical), TRIM61 (20% identical), TRIM60 (20% identical), TRIM17 (20% identical), and 68 more.
Diseases named in the same sentence as TRIM31 in open-access papers:
TRIM31 is named in the same sentence as 74 diseases in open-access papers, as found by Europe PMC text mining. Sharing a sentence is not in itself a finding about the gene and the disease. The quoted sentences say what the papers report.
viral infection (13 papers, 2017 to 2025). "Following viral infection, TRIM31 interacts with MAVS and facilitates K63-linked polyubiquitination at lysine residues 10, 311, and 461 of MAVS." (PMID 39823440, 2025). "As a member of the TRIM-containing proteins, tripartite motif 31 (TRIM31) has been implicated in a variety of pathological processes, including inflammatory diseases, protein quality control, autophagy, viral infection, and carcinoma development (24, –, 27)." (PMID 41294327, 2025). "Upon IAV infection, TRIM31 catalyzes the K63-linked ubiquitination of MAVS and promotes the IFN-I response against virus infection." (PMID 41294327, 2025). "TRIM31 is involved in various pathological events such as inflammatory diseases, protein quality control, autophagy, viral infections, and cancer development." (PMID 39215331, 2024). "As a regulator of Mitochondrial antiviral signaling protein (MAVS) aggregation, TRIM31 can be recruited to mitochondria after viral infection and specifically regulate antiviral signaling mediated by RIG-I-like receptor (RLR) pattern-recognition receptors." (PMID 36620540, 2022). "We observed that the interaction between MAVS and TRIM31 following viral infection was significantly impaired in Usp18−/− MEFs compared with Usp18+/+ MEFs." (PMID 34016972, 2021). "TRIM31 was previously reported to translocate to mitochondria to interact with MAVS following viral infection." (PMID 34016972, 2021). "Due to the positive correlation of TRIM31 with TMPRSS2 and TMPRSS4 genes, it may therefore cause higher susceptibility of viral infections, such as SARS-CoV-2, seen in cancer patients." (PMID 35970857, 2022). "In addition to its crucial role in antiviral processes, TRIM31 also has an important role in promoting viral infection." (PMID 36620540, 2022). "TRIM31 can bind with different adaptor proteins to induce more pro-inflammatory cytokines or interferon through different pathways against fungal pathogens or virus infection in innate immune cells." (PMID 34362877, 2021). "Following viral infection, USP18 is enriched in mitochondria and promotes the mitochondrial translocation of TRIM31 from the cytoplasm and interaction between TRIM31 and MAVS, consequently enhancing TRIM31-mediated K63-linked polyubiquitination and subsequent aggregation of MAVS." (PMID 34016972, 2021). "However, viral infection leads to geranylgeranylation and palmitoylation of Rac1, which inhibits the TRIM31–MAVS interaction and suppresses innate immunity; interestingly, under physiological conditions, Rac1 can also inhibit MAVS aggregation." (PMID 32536927, 2020). "Notably, TRIM31-mediated MAVS aggregation does not occur under RIG-I deficient or non-viral infection conditions, thus it can be considered that RIG-I engagement is required for TRIM31-mediated MAVS aggregation after viral infection." (PMID 32536927, 2020). "Although the authors did not evaluate virus infection directly, Trim31-deficient cells stimulated with poly(I:C) express higher levels of NLRP3 compared to wild-type cells suggesting TRIM31 may regulate NLRP3 downstream of virus recognition." (PMID 28829373, 2017). "Upon viral infection, USP18 is critical for the re-localization of TRIM31 from the cytoplasm to mitochondria and the interaction between TRIM31 and MAVS." (PMID 34016972, 2021). "Moreover, our findings demonstrate that TRIM31 is positively correlated with TMPRSS2-TMPRSS4 genes in GI samples suggesting a possibility of TRIM31 acting alongside with TMPRSS2-TMPRSS4 protease pair in SARS-CoV-2 viral entry and promoting viral infection in GI cells." (PMID 35970857, 2022). "In the light of our findings where TRIM31 is positively correlated with TMPRSS2-TMPRSS4 in GI tumors and knockdown of TRIM31 mediates viral replication and viral processes, developing inhibitors targeting TRIM31 may decrease viral infection efficiency of SARS-CoV-2 in colorectal cancer patients." (PMID 35970857, 2022).
breast carcinoma (11 papers, 2021 to 2025). "TRIM31 was downregulated in lung and breast cancer, and higher expression of the TRIM31 gene is linked to better overall survival of patients." (PMID 36620540, 2022). "Our research showed that TRIM31 expression was decreased in breast cancer tissues and that lower TRIM31 levels were associated with worse survival of breast cancer patients." (PMID 36620540, 2022). "In this study, we verified that TRIM31 expression was downregulated in breast cancer and that low TRIM31 levels were associated with worse survival outcomes than high levels in breast cancer patients." (PMID 34650049, 2021). "Both gain- and loss-of-function assays indicated that TRIM31 inhibits the proliferation, colony formation, migration, and invasion of breast cancer cells." (PMID 34650049, 2021). "TRIM31 acts as a suppressed gene in lung cancer, breast cancer, and endometrial adenocarcinomas in previous studies." (PMID 40661182, 2025). "High-expressed TRIM31 was found in gallbladder cancer, pancreatic cancer, and colorectal cancer while low-expressed in breast cancer." (PMID 38978046, 2024). "Retinoid bound to the promoter of TRIM31 to induce TRIM31 expression and then suppressed the proliferation of breast cancer." (PMID 36620540, 2022). "Retinoid induced proliferation inhibition of breast carcinoma cells by targeting the TRIM31 promoter." (PMID 36620540, 2022). "The Cell Counting Kit-8 (CCK-8) assay showed that TRIM31 suppression increased the viability of breast cancer cells." (PMID 34650049, 2021). "The data indicated that the expression of TRIM31 was significantly reduced in breast cancer tissues." (PMID 34650049, 2021). "TRIM31 was low expressed in breast cancer and the low expression of TRIM31 was negatively correlated with the patient’s survival prognosis." (PMID 34650049, 2021). "Next, we examined the mRNA levels of TRIM31 in breast cancer patients by quantitative real-time polymerase chain reaction (PCR)." (PMID 34650049, 2021). "TRIM31 overexpression significantly suppressed breast cancer cell proliferation and colony formation, as determined by CCK-8 and colony formation assays, respectively." (PMID 34650049, 2021). "To elucidate the molecular mechanism of TRIM31-mediated anti-tumor function in breast cancer, we used proteomics and coimmunoprecipitation-mass spectrometry (MS) to characterize the specific substrate proteins of TRIM31." (PMID 34650049, 2021). "Specifically, TOM1L1 and ESR1 were highly expressed, but MAFF, TNS1, EFEMP2, and TRIM31 were significantly downregulated in breast cancer." (PMID 34151731, 2021).
breast carcinoma (continued). "In this study, we showed that TRIM31 is downregulated in breast cancer tissues and negatively correlated with breast cancer progression." (PMID 34650049, 2021). "Subsequently, we evaluated the correlation of TRIM31 expression with the clinicopathological characteristics of breast cancer patients." (PMID 34650049, 2021). "To explore the function and clinical relevance of TRIM31 in human breast cancer, we first analyzed the mRNA expression of TRIM31 in breast cancer by using RNA-seq data from The Cancer Genome Atlas (TCGA)." (PMID 34650049, 2021). "Collectively, these results suggest that the C–C and RING domains were essential for the tumor suppressor function of TRIM31 in breast cancer." (PMID 34650049, 2021). "More importantly, Kaplan–Meier analysis revealed that breast cancer patients with low TRIM31 levels had worse survival outcomes than those with high levels in the cancer dataset from the Kaplan–Meier Plotter." (PMID 34650049, 2021). "The data indicated that overexpression of TRIM31 inhibited the growth of breast cancer cells, and this effect was rescued by MDM2 overexpression." (PMID 34650049, 2021). "The results showed that TRIM31 mRNA expression was markedly decreased in breast cancer tissues compared with normal breast tissues." (PMID 34650049, 2021). "In this study, we showed that the expression of TRIM31 was decreased in breast cancer tissues and that its overexpression suppressed the proliferation, migration, and invasion of breast cancer cells in vitro and in vivo." (PMID 34650049, 2021). "All these data suggest that TRIM31 acts as a tumor suppressor in breast cancer and may be a valuable prognostic biomarker in breast cancer patients." (PMID 34650049, 2021).
breast carcinoma (continued). "Furthermore, we analyzed TRIM31 expression in breast cancer patients by immunohistochemical staining with a TRIM31 antibody." (PMID 34650049, 2021). "This founding indicated that restoring the expression of TRIM31 may be a new therapeutic strategy for breast cancer." (PMID 34650049, 2021). "Altogether, these results indicate that TRIM31 expression is downregulated in breast cancer and that it may be a valuable prognostic biomarker in breast cancer patients." (PMID 34650049, 2021). "To verify whether TRIM31 was involved in the malignant progression of breast cancer cells in vivo, we first established a xenograft tumor model by subcutaneous injection of TRIM31 or TRIM31-C36A-overexpressing ZR-75-30 cells and control cells into nude mice, respectively." (PMID 34650049, 2021). "Therefore, we further investigated whether these two domains are essential for the tumor suppressor function of TRIM31 in breast cancer." (PMID 34650049, 2021). "Moreover, upregulation of TRIM31 inhibited the migration and invasion of breast cancer cells." (PMID 34650049, 2021). "We next used a lentivirus-mediated expression system to stably overexpress TRIM31 in MCF7 and ZR-75-30 breast cancer cell lines." (PMID 34650049, 2021). "However, the function of TRIM31 in breast cancer progression remains unknown." (PMID 34650049, 2021). "Altogether, these studies have shown that TRIM31 might play a tumor suppressor role in breast cancer, non-small cell lung cancer and the early stage of gastric adenocarcinoma." (PMID 36620540, 2022). "However, the role and mechanism of TRIM31 in breast cancer progression are still not clear." (PMID 34650049, 2021).